GREB1 (growth regulating estrogen receptor binding 1)
Diseases named in the same sentence as GREB1 in open-access papers (continued):
Sharing a sentence is not in itself a finding about the gene and the disease.
breast carcinoma (continued). "PR and GREB1, two genes commonly associated with estrogen responsiveness in breast cancer, are not included in the signature because their expression levels were significantly reduced by H2O2 and menadione treatments but not significantly reduced by the thiol-specific oxidant diamide." (PMID 18631401, 2008). "The results indicated a positive correlation between PSMD14 and several ERα target genes, including GREB1, TFF1, and MCM6, in breast cancer samples." (PMID 38017133, 2024). "GWASs have also demonstrated a genetic overlap between UL and breast cancer, particularly in the ER+ subtype, as well as with endometriosis, involving genes such as WNT4/CDC42, GREB1, ESR1, and follicle-stimulating hormone subunit beta (FSHB)." (PMID 38790186, 2024). "Notably, we demonstrated that ERα-mediated activity could occur through a genomic pathway, stimulating the expression of GREB1 (growth regulation by estrogen in breast cancer 1), a crucial regulator of E2-stimulated epithelial ovarian cancer and granulosa cell tumor cell growth." (PMID 39570927, 2024). "Immunoblotting of samples treated with the lead compound 7e revealed its potent antiestrogenic activity (ERα/GREB1 axis) and induction of PARP cleavage (an apoptosis marker) in breast cancer cells." (PMID 38256865, 2023). "Among them were major regulators of breast cancer cell proliferation, including CCND1, LEF1, KLF9, GREB1, or MAP3K3." (PMID 36076907, 2022). "RNF181 depletion inhibits breast cancer progression in vivo and in vitro, reduces ERα protein level and its target gene expression, such as PS2 and GREB1." (PMID 32973333, 2020). "Other selected genes, SLC40A1, ADAMTS15, THSD4, GREB1, and SLC44A4 have been reported to be related to breast cancer, and ZG16B, FDCSP, and SRARP have been associated with other types of tumors." (PMID 32795265, 2020). "E2­activated HSF1 was transcriptionally potent and several genes essential for breast cancer cells growth and/or ERα action, including HSPB8, LHX4, PRKCE, WWC1, and GREB1, were activated by E2 in a HSF1-dependent manner." (PMID 31614463, 2019). "We found that in mouse ovarian cancer cells, Greb1 is induced by E2 through ESR1 binding to EREs in breast cancer cells." (PMID 29973689, 2018). "To achieve this, we modified a GREB1 locus, using CRISPR/Cas9, in the ERα‐positive breast cancer cell line MCF7 and visualized nascent transcripts using the PP7 reporter system." (PMID 29476006, 2018). "Conversely, ER-negative breast cancer cell lines MDA-MB 231 and SUM 225 express GREB1 at lower levels." (PMID 30154312, 2018). "Such ligands induced breast cancer cell proliferation in a manner that was predicted by the canonical recruitment of the coactivators NCOA1/2/3 and induction of the GREB1 proliferative gene." (PMID 27107013, 2016). "Ligand profiling using our quantitative bioassays revealed a wide range of ligand‐induced GREB1 expression, reporter gene activities, ERα‐coactivator interactions, and proliferative effects on MCF‐7 breast cancer cells (Figs EV1 and EV2A–J)." (PMID 27107013, 2016). "The expression of miR-26a and miR-26b in human breast cancer cells suppressed cell growth, at least partly through repression of CHD1, GREB1 and KPNA2." (PMID 24735615, 2014). "In the present study, we evaluated the effect of BPAF on endogenous transcription of TFF1, GREB1 and CTSD in human breast cancer cells." (PMID 24727858, 2014). "We further evaluated the expression levels of CHD1, GREB1 and KPNA2 mRNA in these breast cancer specimens by qRT-PCR." (PMID 24735615, 2014). "GREB1, CHD1 and KPNA2 were identified as novel targets of miR-26a/b and were demonstrated to be necessary for estrogen-promoted ER+ breast cancer cell proliferation." (PMID 24735615, 2014). "The gene cluster included TFF1, PGR, GREB1, and other ER-sensitive genes such as insulin-like growth factor binding protein 1 (IGFBP1), breast carcinoma amplified sequence, and fibulin." (PMID 23938070, 2013).
breast carcinoma (continued). "We conclude that in ER-positive breast cancer cells, LRH-1 promotes cell proliferation by enhancing ERα mediated transcription of target genes such as GREB-1." (PMID 22359603, 2012). "The most significant ones include TFF1, CCND1, IGFBP4, C3, ADORA1, GREB1, and MYC, which have been shown by candidate gene analysis to be estrogen regulated genes in breast cancer cell lines." (PMID 21878096, 2011). "We therefore tested the same TFF1 and GREB1 probes on ERα–positive MCF-7 breast cancer cells, which have also been reported to demonstrate rapid nuclear colocalisation of TFF1 and GREB1 upon E2 addition." (PMID 20421946, 2010). "Given this potential discrepancy, we sought to re-examine the nuclear organisation of TFF1 and GREB1 upon E2 stimulation in normal-like MCF10A and cancerous MCF-7 breast cancer cell lines and in primary HMECs." (PMID 20421946, 2010). "The lead compounds showed a dual mechanism of action by inhibiting S6 kinase and promoting Bcl-2 phosphorylation at 0.9 μM, without significantly affecting hormonal breast cancer targets such as ERα, GREB1, and AR." (PMID 41463068, 2025). "In hormone receptor-positive tumors, GATA3 modulates cell proliferation through estrogen-responsive genes (e.g., ESR1 and GREB1), while TRPS1 may similarly influence hormonal signaling in breast cancer." (PMID 40969274, 2025). "For instance, GREB1 is a key regulatory factor of the estrogen receptor, influencing chromatin accessibility through interactions with PRC1.2, ERα, and FOXA1, with FOXA1 being a notable biomarker for the luminal breast cancer subtype." (PMID 39452108, 2024). "Next, we confirmed the nuclear localization of GREB1 in MNA+ NB cells, although some cytoplasmic staining was also observed, in support of its recently uncovered cytoplasmic function in ER+ breast cancer as an O-GlcNAc glycosyltransferase." (PMID 37611092, 2023). "NUPR1 could also active autophagy and bind to the promoter regions of some autophagy-related genes, such as BECN1, GREB1, RAB31, PGR, CYP1B1, thereby regulating breast cancer metastasis and transcription." (PMID 37626099, 2023). "The breast cancer cell lines MCF7 and T47D are very sensitive to a selection of antihormonal drugs, which prompted us to investigate whether ESR1, PGR, and GREB1 protein show similar abundance profiles across the NCI60 panel as their p-sites." (PMID 32686665, 2020). "Of note, earlier studies of GREB1 in breast cancer did not report any effect on ER DNA binding, which we confirmed by GREB1 knockdown in MCF7 breast cancer cells." (PMID 30644358, 2019). "Any possible correlation between ESR1 and GREB1 expression was also examined to determine whether GREB1 correlates with ESR1 in ovarian cancer, as reported in breast cancer." (PMID 29973689, 2018). "GREB1 and PGR play a critical role in ERα genomic activity in breast cancer cells." (PMID 29608602, 2018). "Additionally, the majority of breast cancer cell lines, including MCF-7, T-47D, and BT-474, are ER-positive and express GREB1 at high levels." (PMID 30154312, 2018). "Furthermore, LSD1 knockdown in breast cancer cells blocked the estrogen-mediated transcription of TFF1 and GREB1 by inhibiting the interaction between the TFF1 and GREB1 loci and the interchromatin granules containing transcription-related factors." (PMID 28811844, 2017). "Interestingly, ten highly ranked statistically significant putative regSNVs (p < 1.0E-03) appeared close to genes previously shown to be oncogenic in breast cancer such as PVT1, IGF1R, and GREB1." (PMID 27964748, 2016). "Our data highlighting that the expression of GLI1 correlates with ESR1, pS2 and GREB1 using a publicly available dataset, suggest that GLI1 may represent a gene with implications in breast cancer." (PMID 27689403, 2016).
breast carcinoma (continued). "We have therefore identified a novel estrogen/MYC/miR-26 axis that mediated estrogen stimulated cell growth via CHD1, GREB1 and KPNA2 and suggest that upregulation of miR-26a and miR-26b may be considered as novel strategy for breast cancer therapy." (PMID 24735615, 2014). "Sites within the fourth intron of CCND1 (Cyclin D1) and the Greb1 (growth regulation by oestrogen in breast cancer 1) promoter were used as negative and positive control, respectively, for FOXA1 binding." (PMID 24265722, 2013). "Recently, a study reported an association between serum levels of estradiol and gene expression of trefoil factor 1 (TFF1), growth regulation by estrogen in breast cancer 1 (GREB1), PDZ domain containing 1 (PDZK1) and progesterone receptor (PGR) in ER+ breast carcinomas." (PMID 21812955, 2011). "NRIP1, GREB1, and ABCA3 are all genes found to be ER responsive in at least two cell lines; they have a discernable ERE around the TSS, blocked by ICI and not inhibited by CHX, and their expression can discern ER status in breast cancers." (PMID 15345050, 2004). "GREB1-ER interactions in nearly half of ER+ primary breast cancers (non-TNBC)." (PMID 39777114, 2024). "Treatment with ICI.182.780 or GREB1 knockdown increased PAI-1 mRNA expression in MCF7 breast cancer cells and GREB1 formed a complex with Smad2/3 in MCF7 cells, suggesting that GREB1 functions as a negative regulator of TGFβ signaling not only in HB but also breast cancer cells." (PMID 31462641, 2019). "However, the average expression level of GREB1 was slightly lower in breast cancers (P > 0.05) than in normal breast tissues." (PMID 24735615, 2014). "We found BPAF stimulated the endogenous transcription of TFF1, GREB1 and CTSD genes through both dose and time-dependent manners in ERα-positive T47D and MCF7 human breast cancer cells, but not in ERα-negative MDA-MB-231 cells." (PMID 24727858, 2014). "Comparing the expression of these genes in breast carcinomas and normal breast tissue, neither AREG nor GREB1 are differentially expressed between normal breast tissue and breast carcinomas." (PMID 21812955, 2011). "The inclusion of GREB1, OSR1, and FAM83D, which are not in the PAM50 gene signature, highlights the potential of our integrative approach to reveal prognostic markers related to breast cancer intrinsic subtypes." (PMID 39452108, 2024). "To evaluate the effect of BPAF on endogenous transcription, we conducted the real-time PCR to detect mRNA levels of estrogen responsive genes, such as TFF1, GREB1 and CTSD in ERα-positive T47D and MCF7 breast cancer cell lines and ERα-negative MDA-MB-231 breast cancer cell line." (PMID 24727858, 2014). "When GREB1 protein expression was examined in cancer cell lines using an anti-GREB1 antibody (#1) that recognizes the N-terminal region of GREB1, full-length GREB1 (216 kDa) was detected only in HepG2 (hepatoblastoma) and MCF7 (breast cancer) but not in melanoma cell lines (left blot)." (PMID 37658191, 2023). "Moreover, high GREB1 expression may not be exclusive to MNA+ NB, as occasional MNA− NBs also express high GREB1 levels (e.g., NB69 cells), likely through distinct mechanisms and with oncogenic functions, such as is described in ER+ breast cancers and prostate adenocarcinomas." (PMID 37611092, 2023).
endometriosis (36 papers, 2014 to 2025). The growth of functional endometrial tissue in anatomic sites outside the uterine body. "GREB1 (codes for Growth Regulating Estrogen Receptor Binding 1) is a well-characterized endometriosis-associated gene." (PMID 41377979, 2025). "The multiple SNPs of GREB1 constitutes most consistently associated gene with endometriosis population." (PMID 38431630, 2024). "Growth regulating oestrogen receptor binding 1 (GREB1), an early response gene in the ER-regulated pathway, was associated with endometriosis, uterine fibroids and ovarian cancer." (PMID 37159502, 2023). "Research indicates a link between the 2p25.1 region, located near the GREB1 gene, and the risk of endometriosis." (PMID 34638893, 2021). "Their studies indicate a correlation between 2p25.1 region, located close to the GREB1 gene, and the risk of endometriosis." (PMID 33153202, 2020). "A genome-wide association meta-analysis of 4604 endometriosis cases and 9393 controls of Japanese and European ancestry established an association of rs13394619 polymorphism in GREB1 with endometriosis." (PMID 32549322, 2020). "Results from the analysis of both discovery and replication samples did provide support for near genome-wide significant association for rs6542095 near IL1A and significant association of the splice variant rs13394619 at the GREB1 locus with endometriosis." (PMID 28900119, 2017). "No variant reached the threshold of genome-wide significance for association with endometriosis, but eight loci associated with P value<1 × 10−6, including the previously reported GREB1 locus and seven novel loci." (PMID 27453397, 2016). "The underlying biological mechanism by which GREB1 plays a role in hormone-responsive tissues especially estrogen-stimulated cell proliferation in endometriosis remains to be elucidated." (PMID 24676469, 2014). "GREB1 has a truncated isoform, GREB1c, and we demonstrate that splicing events in ovarian and uterine tissue associated with this isoform increase risk of endometriosis while splicing events associated with the canonical isoform (GREB1a) are associated with decreased disease risk." (PMID 41377979, 2025). "Furthermore, single nucleotide polymorphisms around the GREB1 locus have been identified in endometriosis patients." (PMID 30154312, 2018). "Thus, future work should address the possibility that mutations in GREB1 predispose women to hormone-related diseases including endometriosis and postmenopausal osteoporosis." (PMID 30154312, 2018). "For instance, SYNE1 and GREB1 showed specific associations with the uterine disorders cluster, suggesting that these genes might play distinct roles in the pathogenesis of these phenotypic presentations of endometriosis." (PMID 39315247, 2024). "Only rs12037376 (CDC42/WNT4), rs71575922 (SYNE1/ESR1), and rs77294520 (GREB1) associate with leiomyoma after correction for the number of tests (P < 0.05/19 = 2.6 × 10−3), with all three variants showing the same direction of effect for endometriosis and leiomyoma (logistic regression)." (PMID 30194396, 2018). "We identified 23 cellular contexts in which GREB1 expression is elevated in cells from donors with endometriosis, mostly from the cells and nuclei sampled during the secretory phase and from donors exposed to exogenous hormones." (PMID 41377979, 2025). "GREB1 and SYNE1 also contain overlapping signals for infertility and endometriosis, but there is strong evidence against shared causal variants (PP >75%)." (PMID 40229599, 2025). "On the other side, we found that GREB1 promotes estrogen-driven endometriosis progression in an in vivo mouse model and promotes the proliferation of human endometriotic stromal and epithelial cells in vitro by functioning as an ER cofactor." (PMID 38431630, 2024). "We chose to focus on endometriosis as this is estrogen-driven pathology and GREB1 SNPs were reported in this genealogical condition." (PMID 38431630, 2024).
endometriosis (continued). "Examining the functional relevance of these individual SNPs of GREB1 in endometriosis disease progression is of our immediate future focus." (PMID 38431630, 2024). "To explore this, we investigated the role of GREB1 in one of the prominent endometrial pathology, endometriosis." (PMID 38431630, 2024). "Next, we used this same model to induce endometriosis in Greb1 KO and WT littermate mice and found that Greb1 KO mice developed smaller endometriotic lesions than did WT littermates." (PMID 38431630, 2024). "While GREB1 and SYNE1 also contain overlapping signals for infertility and endometriosis, there is strong evidence against shared causal variants (PP>75%, Supp." (PMID 38562841, 2024). "A meta-analysis reported that genes associated with endometriosis that were involved in hormone signalling (WNT4/CDC42, GREB1, ESR1, FSHB) were also associated with diagnosis of fibroids." (PMID 35514537, 2022). "It is worth noting that three genetic variants in the area of GREB1 (close to rs13394619) and CDKN2B-AS1 (close to rs1537377) also showed nominally significant associations with endometriosis." (PMID 34638893, 2021). "Three coding variants in GREB1 and CDKN2B-AS1 were nominally associated with the risk of endometriosis." (PMID 34298916, 2021). "There have been described other putative functions of GREB1 in various conditions such as ovarian cancer, prostate cancer, endometriosis, lung cancer, and hepatoblastoma." (PMID 32549322, 2020). "It is noteworthy that three variants within GREB1 area (close to rs13394619) and CDKN2B-AS1 (close to rs1537377) also demonstrated nominally significant relationships with endometriosis." (PMID 33153202, 2020). "Our UL GWAS meta-analysis indicates that genes previously associated with endometriosis and involved in hormone-signaling pathways are also associated with UL (WNT4/CDC42, GREB1, ESR1, and FSHB)." (PMID 31649266, 2019). "Five mSNPs associated with DNAm probe sites closest to GREB1, C11orf46, NR2C1, KDR and WNT4 are located within regions associated with endometriosis risk." (PMID 30871624, 2019). "Genetic differences play a significant role in risk for endometriosis; a recent meta-analysis of over 170,000 endometriosis patients and almost 200,000 controls revealed 14 genetic regions of interest, including WNT4, GREB1, IL1A, and CDKN2B." (PMID 30134794, 2018). "SNP rs13394619 is the GREB1 GWA signal that showed associations with both all (P = 7.4 × 10−7) and Grade B (P = 0.032) endometriosis." (PMID 28900119, 2017). "GREB1 is an excellent candidate in endometriosis pathogenesis because of its known estrogen-responsive properties and previous reports of altered GREB1 expression both at mRNA and protein levels." (PMID 28900119, 2017). "Specifically, GREB1 (a GWAS-linked gene induced by WNT signaling) was significantly upregulated while DKK1 (WNT inhibitor) was significantly downregulated in both dStromal early and dStromal mid cells in endometriosis." (PMID 39198675, 2024). "GREB1, which has been identified in previous GWASs, is a target gene of E2/ERα and functions as a chromatin-bound estrogen receptor cofactor in endometriosis, promoting the growth and proliferation of estrogen-responsive cells." (PMID 39062866, 2024). "In contrast, GREB1 was controlled by estrogen and contributed to estrogen effects in endometriosis." (PMID 38431630, 2024). "One gene that may participate in both physiologically normal menstrual cycle/pregnancy-mediated changes to the endometrium and in pathological changes that occur in endometriosis is Growth Regulation by Estrogen in Breast Cancer 1 (GREB1)." (PMID 38431630, 2024). "In premenopausal women with endometriosis, increased expression of GREB1 has been reported." (PMID 32549322, 2020).